RNU1-5P (RNA, U1 small nuclear 5, pseudogene)
Synonyms: RNU1-5
Gene: Small nuclear RNA gene on chromosome 1 (16,873,708 to 16,873,851, forward strand). Ensembl gene ENSG00000277234.
Homologues: Orthologues: chimpanzee U1 (99% identical), macaque U1 (95% identical), dog U1 (73% identical), guinea pig U1 (67% identical). Paralogues in human: RNU1-6P (97% identical), U1 (97% identical), RNU1-143P (95% identical), RNU1-153P (95% identical), RNU1-68P (95% identical), U1 (95% identical), RNU1-19P (78% identical), RNU1-1 (77% identical), RNU1-2 (77% identical), RNU1-27P (77% identical), RNU1-28P (77% identical), RNU1-3 (77% identical), and 134 more.